PHKA1 (phosphorylase kinase regulatory subunit alpha 1)
Description:
Phosphorylase b kinase catalyzes the phosphorylation of serine in certain substrates, including troponin I. The alpha chain may bind calmodulin.
Synonyms: PHKA
Tractability: Small molecule: a structure with a bound ligand is known; a high-quality ligand is known. Antibody: UniProt places it where antibodies can reach, with high confidence; its Gene Ontology location is reachable by antibodies, with medium confidence. PROTAC: ubiquitination databases record sites on it; its protein half-life has been measured; a small molecule that binds it is known.
Gene: Protein-coding gene on chromosome X (72,578,814 to 72,714,327, reverse strand). Ensembl gene ENSG00000067177.
Subcellular location: Cell membrane
Subcellular location (Human Protein Atlas): Cytosol; Vesicles
Pathways (Reactome):
Metabolism: Glycogen breakdown (glycogenolysis)
Gene Ontology:
Molecular function: phosphorylase kinase activity; calmodulin binding
Biological process: glycogen catabolic process; positive regulation of glycogen catabolic process; generation of precursor metabolites and energy; glycogen metabolic process; carbohydrate metabolic process
Cellular component: phosphorylase kinase complex; cytosol; cytoplasm; plasma membrane
Gene-disease validity (ClinGen):
ClinGen rates the evidence that PHKA1 causes each of these diseases.
glycogen storage disease IXd (X-linked): Definitive. A benign form of phosphorylase kinase deficiency caused by variants in PHKA1, characterized by exercise intolerance, myalgia, muscle cramps, myoglobinuria, and progressive muscle weakness.
Homologues: Orthologues: macaque PHKA1 (99% identical), chimpanzee PHKA1 (97% identical), rabbit PHKA1 (96% identical), guinea pig PHKA1 (95% identical), pig PHKA1 (95% identical), mouse Phka1 (95% identical), rat Phka1 (94% identical), dog PHKA1 (80% identical), tropical clawed frog phka2 (77% identical). Paralogues in human: PHKA2 (69% identical), PHKB (32% identical).
Diseases named in the same sentence as PHKA1 in open-access papers:
PHKA1 is named in the same sentence as 26 diseases in open-access papers, as found by Europe PMC text mining. Sharing a sentence is not in itself a finding about the gene and the disease. The quoted sentences say what the papers report.
Glycogen Storage Disease (4 papers, 2021 to 2024). "GSDIX is a group of glycogenoses caused by hepatic phosphorylase kinase deficiency, a hexadecameric enzyme comprising four copies each of four unique subunits encoded by four different genes; PHKA1, PHKA2, PHKB, and PHKG2." (PMID 34946936, 2021).
gastrointestinal stromal tumor (2 papers, 2018 to 2022). "Prakash and his colleges demonstrated that the increased expression of PHKA1 was associated with younger ages of gastrointestinal stromal tumor patients." (PMID 29954422, 2018). "In addition, the increased expression of PHKA1 was associated with younger ages of gastrointestinal stromal tumor patients." (PMID 35468826, 2022).
metabolic myopathy (2 papers, 2010 to 2025). A group of rare inherited disorders characterized by a deficiency of enzymes that are involved in metabolic pathways that affect muscles. "A rhabdomyolysis and metabolic myopathy gene panel revealed a pathogenic nonsense variant in PHKA1 (c.892C>T, p.Arg298Ter)." (PMID 41213961, 2025). "A rhabdomyolysis and metabolic myopathy panel revealed a deletion spanning exons 30-32 in the PHKA1 gene (c.3244-155_3620del), classified as likely pathogenic." (PMID 41213961, 2025). "Allelic variants in Phka1 in human populations are associated with metabolic myopathy." (PMID 20886071, 2010).
Myalgia (2 papers, 2015 to 2025). "Muscle symptoms associated with mutations in PHKA1 are usually mild and include exercise-induced myalgia and cramps, fatigue and myoglobinuria." (PMID 25929793, 2015). "Symptomatic muscle PK deficiency may be seen in association with PHKB (OMIM #172490) and PHKA1 (OMIM #311870) mutations, although a mild transitory form of muscle weakness and myalgia after strenuous exertion has been recently reported in two patients with PHKG2 mutations." (PMID 25929793, 2015).
Cognitive impairment (1 paper, 2025). Abnormal cognition is characterized by deficits in thinking, reasoning, or remembering. "In one patient, who presented with short stature, cognitive impairment, obesity, and progressive myopathy, a novel frameshift mutation (c.2594delA) in the PHKA1 gene was found." (PMID 40428406, 2025).
coronary heart disease (1 paper, 2025). "ATP7A and PHKA1 are likely related to the cardiovascular system, EBP is associated with coronary heart disease and skeletal-related conditions, ZFX is known to be involved in animal size and ovarian failure, and SMC1A is implicated in premature ovarian failure." (PMID 39940742, 2025).
epilepsy (1 paper, 2022). A brain disorder characterized by episodes of abnormally increased neuronal discharge resulting in transient episodes of sensory or motor neurological dysfunction, or psychic dysfunction. "Hence, AEDs exerted a therapeutic effect on vasogenic epilepsy derived from endothelial CDK5 loss, which results in downregulating epilepsy‐related Phka1 and Btaf1 and upregulating synaptic function‐related Grin1 and Magt1." (PMID 35770064, 2022). "The RT‐PCR results suggested that the mRNA levels of Btaf1, Phka1, and Nav1, which possess a strong correlation with epilepsy, were upregulated significantly." (PMID 35770064, 2022). "Together, the mRNA levels of Btaf1, Phka1, Nav1, and Magt1 were related to epilepsy." (PMID 35770064, 2022). "Moreover, to clarify the effects of AEDs on the mRNA levels of epilepsy‐related and synapse‐related proteins in Cdh5‐CreERT2;CDK5f/f mice, the mRNA levels of Btaf1, Phka1, Nav1, Bdnf, Magt1, and Grin1 were confirmed by qRT‐PCR." (PMID 35770064, 2022). "Accordingly, changes of synapse‐related gene (Phka1, Btaf1, Magt1, and Grin1) and aberrant alternation of NMDA receptors, PSD95, phosphorylation of CaMKII were found in the hippocampus of spontaneous epilepsy mice." (PMID 35770064, 2022).
limb-girdle muscular dystrophies (1 paper, 2021). "While most of these patients were affected by recessive or dominant forms of limb-girdle muscular dystrophies, one of them had a pathogenic variant in PHKA1 associated with the X-linked form of muscle glycogenosis." (PMID 34149409, 2021).
melanoma (1 paper, 2021). A malignant, usually aggressive tumor composed of atypical, neoplastic melanocytes. "Our findings support the role of ALK, ROCK1 and PHKA1 as a protein kinase for activating the metabolism of the energy sources from macronutrients used by the melanoma to support growth, proliferation and survival." (PMID 34199079, 2021). "Non-metabolism-related proteins (BRCA1, phosphorylase B kinase regulatory subunit: PHKA1, tyrosine-protein kinase receptor: ALK and rho-associated protein kinase: ROCK1) correlated to melanoma development differed among all groups." (PMID 34199079, 2021). "Lactate secretion cooperation to promote melanoma metastasis via phosphorylation enzyme is involved in the pathway for PHKA1 and lipid metabolism, as well as glucose metabolism for ROCK1." (PMID 34199079, 2021).
Mitochondrial myopathy (1 paper, 2022). "All patients had mutations in the PHKA1 gene and the patient with mitochondrial myopathy also had a mutation in the MT-TL1 gene." (PMID 36034300, 2022).
prostate carcinoma (1 paper, 2022). A carcinoma that arises from epithelial cells of the prostate gland. "Research has shown that PHKA1, as an important gene related to glycogen metabolism, is related to the metastasis of prostate cancer." (PMID 35468826, 2022).
X-linked muscle glycogenosis (1 paper, 2022). "PHKA1 plays a key role in glycogen metabolism and PHKA1 mutations cause glycogen storage disease type 9D, also known as X-linked muscle glycogenosis." (PMID 35468826, 2022).
myopathy (5 papers, 2010 to 2022). A disease of the muscle in which the muscle fibers do not function properly. "GSD IXd, caused by mutations in the PHKA1 gene, is an ultra-rare type of mild myopathy with exercise intolerance." (PMID 36034300, 2022). "Mutations in PHKA1 cause GSD type VIII which is usually a mild myopathy with slight elevation of plasma creatine kinase concentration and muscle glycogen content." (PMID 29695245, 2018).
cancer (3 papers, 2021 to 2026). A tumor composed of atypical neoplastic, often pleomorphic cells that invade other tissues. "PHKA1 is a regulator of glycogen metabolism, but its role in cancer has been less studied." (PMID 35884444, 2022). "The PHKA1 catalyses the phosphorylation of serine, whereas ROCK1 catalyses that of serine/threonine in cancer development, progression and metastasis." (PMID 34199079, 2021).
metabolic disorders (1 paper, 2025). "It is a rare and mild metabolic disorder, with only 19 reported cases of PHKA1 mutations." (PMID 40923014, 2025).
PHKA1 also shares sentences with these, for which no sentence is quoted: Alzheimer disease (1 paper); asthma (1); Chronic Lymphocytic Leukemia (1); colorectal carcinoma (1); hepatic (1); Liver Carcinoma (1); muscular dystrophies (1); Obesity (1); ovarian failure (1); premature ovarian failure (1); tumour (1).